ACTBL2 (actin beta like 2)
Description:
Actins are highly conserved proteins that are involved in various types of cell motility and are ubiquitously expressed in all eukaryotic cells.
Synonyms: DKFZp686D0972; ACT
Tractability: PROTAC: ubiquitination databases record sites on it; its protein half-life has been measured.
Gene: Protein-coding gene on chromosome 5 (57,480,018 to 57,482,811, reverse strand). Ensembl gene ENSG00000169067.
Subcellular location: Cytoplasm, cytoskeleton
Gene Ontology:
Molecular function: protein binding; protein kinase binding; structural constituent of postsynaptic actin cytoskeleton
Biological process: axonogenesis; cell motility; postsynaptic actin cytoskeleton organization
Cellular component: extracellular exosome; extracellular region; actin cytoskeleton; actin filament; axon; cytoplasm; glutamatergic synapse; membrane; NuA4 histone acetyltransferase complex; cytoskeleton; synapse
Genetic constraint (gnomAD): Loss-of-function variants: 30 observed, 24.99 expected, observed/expected ratio (o/e) 1.2, 90% interval 0.9 to 1.62. The upper end of that interval is the gene's LOEUF score, 1.62, which puts it in group 6 of 6, group 1 being the genes least tolerant of losing a copy. Missense variants: 524 observed, 516.91 expected, observed/expected ratio (o/e) 1.01, 90% interval 0.94 to 1.09. Synonymous variants: 173 observed, 194.05 expected, observed/expected ratio (o/e) 0.89, 90% interval 0.79 to 1.01.
Homologues: Orthologues: macaque ACTBL2 (99% identical), guinea pig ACTBL2 (97% identical), mouse Actbl2 (97% identical), dog ACTBL2 (97% identical), rat Actbl2 (97% identical), pig ACTBL2 (97% identical), rabbit ACTBL2 (93% identical). Paralogues in human: ACTB (91% identical), ACTG1 (91% identical), ACTC1 (88% identical), ACTA2 (88% identical), ACTG2 (88% identical), ACTA1 (88% identical), ACTR1B (53% identical), ACTR1A (51% identical), ACTR2 (48% identical), ACTRT3 (47% identical), ACTRT2 (47% identical), ACTRT1 (47% identical), and 14 more.
Diseases named in the same sentence as ACTBL2 in open-access papers:
ACTBL2 is named in the same sentence as 16 diseases in open-access papers, as found by Europe PMC text mining. Sharing a sentence is not in itself a finding about the gene and the disease. The quoted sentences say what the papers report.
melanoma (6 papers, 2016 to 2023). A malignant, usually aggressive tumor composed of atypical, neoplastic melanocytes. "Functional examinations in human melanoma cells revealed an interaction between ACTBL2 and gelsolin in the course of cellular lamellipodia formation." (PMID 38114558, 2023). "Comprehensive analyses of human melanoma cells revealed a specific interaction between polymerized ACTBL2 and the multifunctional actin-binding protein gelsolin in the edge of lamellipodia as protrusions conducting cellular migration." (PMID 38114558, 2023). "We also discovered that ACTBL2 is expressed at a very low level in several melanoma cell lines, but a small subset of cells exhibited a high ACTBL2 expression." (PMID 33558623, 2021). "Indeed, the association of ACTB with a wide range of cancer types (liver, renal, colorectal, gastric, pancreatic, esophageal, lung, breast, prostate, and ovarian cancers and leukemia, melanoma, and lymphoma) has been explained and that of ACTBL2 in some hepatocellular carcinoma has been reported." (PMID 28018022, 2016). "ACTBL2 as a binding partner of gelsolin (GSN), has also been attributed to increasing cell proliferation in human colorectal adenocarcinoma and melanoma cells." (PMID 35770079, 2022). "Next, we checked the expression levels of ACTBL2, ACTB, and ACTG1 in five melanoma cell lines." (PMID 33558623, 2021).
ovarian carcinoma (5 papers, 2016 to 2024). A malignant neoplasm originating from the surface ovarian epithelium. "Actin beta-like 2 (ACTBL2), a novel described actin isoform showing 92% structural similarity to ß-actin, was found to be a putative risk gene in ovarian cancer." (PMID 34631538, 2021). "Since ACTBL2 expression was shown to be associated with an impaired prognosis of ovarian cancer patients, putatively enhanced by its promigratory characteristics, a reduction of intracellular levels of ACTBL2 might result in prognostically favorable alterations in tumor biology." (PMID 34631538, 2021). "Incorporating the somatic mutations in non-coding regions revealed a slightly broader spectrum of findings, of which potentially significant discoveries include UBTF in Ovarian Cancer (OV) and ACTBL2 in HNSC." (PMID 38241355, 2024). "This study characterizes the subset of ACTBL2-expressing TILs in epithelial ovarian cancer (EOC) and elucidates their prognostic influence on the overall survival of EOC patients with special regard to different histological subtypes." (PMID 38114558, 2023). "The present study is the first one to ever investigate the expression of ACTBL2 in TILs with special regard to their prognostic significance on the overall survival of ovarian cancer patients." (PMID 38114558, 2023). "Concluding, our study provides for the first time significant evidence of the favorable prognostic impact of ACTBL2-expressing TILs in epithelial ovarian cancer with regard to different histological subtypes." (PMID 38114558, 2023). "Actin beta-like 2 (ACTBL2) was recently identified as a new mediator of migration in ovarian cancer cells." (PMID 38114558, 2023). "Intending to investigate the distribution of ACTBL2-positive tumor-infiltrating leukocytes, immunohistochemical staining was analyzed in a cohort of 156 ovarian cancer patients." (PMID 38114558, 2023). "Aiming at characterizing the subset of ACTBL2-expressing TILs in epithelial ovarian cancer with special regard to putative immune-mediated antitumoral effects, immunofluorescence double-staining was performed." (PMID 38114558, 2023). "Intending to further investigate the prognostic significance of ACTBL2 expression in ovarian cancer, a univariate analysis of overall survival (OS) was performed." (PMID 34631538, 2021). "Experiments assessing the basal expression of ACTBL2 revealed significantly elevated ACTBL2 levels in all tested ovarian cancer cell lines compared to the benign control." (PMID 34631538, 2021). "In summary, our study provides for the first time significant evidence on the prognostic relevance of ACTBL2 expression in epithelial ovarian cancer." (PMID 34631538, 2021). "Intending to elucidate the cellular function of ACTBL2 in terms of ovarian cancer etiology and progression, further in vitro experiments were performed." (PMID 34631538, 2021). "The present study aims at identifying and characterizing the subset of ACTBL2-expressing TILs in epithelial ovarian cancer and at elucidating their prognostic influence on the overall survival of EOC patients with special regard to different histological subtypes." (PMID 38114558, 2023). "Intending to define the exact cellular composition of ACTBL2-expressing leukocytes in ovarian cancer, various common markers for the most frequent immune cell subtypes have been investigated—CD4 (T-helper cells), FOXP3 (regulatory T-cells) and CD56 for natural killer cells." (PMID 38114558, 2023). "Taken together, our results suggest that the favorable prognostic effect of ACTBL2-expressing TILs in ovarian cancer is attributed to the presence and close interaction of activated cytotoxic T-cells and macrophages, probably in their function as antigen-presenting and T-cell-attracting cells." (PMID 38114558, 2023).
ovarian carcinoma (continued). "Further studies evaluating the targeted antiproliferative use of Etomoxir are necessary to precisely analyze its impact on NFAT5 and ACTBL2 expression in vitro and in vivo with special regard to consecutively altered cellular functions in epithelial ovarian cancer." (PMID 34631538, 2021). "However, further experiments are required to assess the potential of Etomoxir of being a new putative mechanism to directly counteract the effects of increased ACTBL2 expression in ovarian cancer cells." (PMID 34631538, 2021). "Summarizing, our findings suggest that the downregulation of ACTBL2 results in a significant decrease in viability, proliferation and migration of ovarian cancer cells, inversely supporting our hypothesis regarding the cellular function of ACTBL2." (PMID 34631538, 2021). "Moreover, ACTBL2 silencing significantly inhibited the proliferation of ovarian cancer cells (p=0.012)." (PMID 34631538, 2021). "Nonetheless, as the analyzed cohort contained very few cases of distant metastasis, more patients’ data is yet to be collected to further assess the contribution of ACTBL2 to enhanced cellular motility in the course of ovarian cancer development with special regard to metastatic mechanisms." (PMID 34631538, 2021). "Additionally, positive ACTBL2 expression (p=0.013), as previously defined, was found to be a novel and statistically independent prognostic factor for impaired overall survival of ovarian cancer patients." (PMID 34631538, 2021). "We also identified the additional CTCFL targets ACTBL2, MALT1, and PCDH7 to be predictive for ovarian cancer treatment outcomes." (PMID 35132075, 2022). "Concluding, the present study investigated the carcinogenetic and prognostic impact of ACTBL2 and NFAT5 in epithelial ovarian cancer by elucidating their expression pattern in EOC patients and their functional molecular interplay in vitro." (PMID 34631538, 2021). "The present study aimed at elucidating the functional role of ACTBL2 and NFAT5 in epithelial ovarian cancer, intentionally assisting to obtain new findings on its etiology with regard to carcinogenetic and disease-promoting mechanisms." (PMID 34631538, 2021). "Aiming to assess molecular biological mechanisms regulating the function of ACTBL2, the impact of NFAT5 on ovarian cancer cells was further investigated." (PMID 34631538, 2021). "The expression of ACTBL2 and NFAT5 was examined in tissue microarrays of 156 ovarian cancer patients by immunohistochemistry." (PMID 34631538, 2021). "The impact of Actin beta-like 2 (ACTBL2), a novel described actin isoform, on epithelial ovarian cancer (EOC) biology has not been investigated so far." (PMID 34631538, 2021). "In sum, our results show for the first time a functional relation between NFAT5 and ACTBL2 in ovarian cancer, with NFAT5 silencing regulating the effect of ACTBL2 on cellular functions, predominantly resulting in a decreased migratory potential of UWB1.289 cells." (PMID 34631538, 2021). "An additionally performed correlation analysis of ACTBL2 and NFAT5 expression using the TIMER database revealed a positive correlation trend between both genes (Cc=0.103, p=0.073), hinting at their previously outlined functional relation in epithelial ovarian cancer." (PMID 34631538, 2021). "By analyzing the expression pattern of Actin beta-like 2 in 156 EOC patients, we could show that ovarian cancer of high-grade serous histology displayed a significantly higher combined cytoplasmic and membranous ACTBL2 expression than specimens of other histological subtypes." (PMID 34631538, 2021).
hepatocellular carcinoma (3 papers, 2014 to 2021). A malignant tumor that arises from hepatocytes. "Moreover, a high abundance of ACTBL2 in hepatocellular carcinoma was associated with altered cellular growth properties and an impaired postoperative disease-free survival of affected patients." (PMID 34631538, 2021). "Whereas studies revealed an upregulation of ACTBL2 in pancreatic, colorectal and hepatocellular carcinoma, investigations focusing on its carcinogenetic impact in gynecological malignancies are still missing." (PMID 34631538, 2021). "By performing in silico analyses, we showed that the promotor sequence of the human ACTBL2 gene—enconding κ-actin, a novel member of the actin family that was originally detected in hepatoma cells —contains several putative NFAT5 binding sites." (PMID 25520667, 2014).
serous carcinoma (2 papers, 2021 to 2023). "In addition, an infiltration by ACTBL2-expressing leukocytes was significantly associated with low grading of serous carcinoma (Cc = 0.200, p = 0.025)." (PMID 38114558, 2023). "Moreover, high levels of ACTBL2 correlated significantly with high grading of serous carcinoma (p=0.003, Cc=0.253)." (PMID 34631538, 2021).
Serous Ovarian Cancer (2 papers, 2021 to 2023). "In line with the obtained results concerning the total cohort, an infiltration by ACTBL2-positive leukocytes was identified as a statistically independent prognostic marker for the overall survival of patients with low-grade serous ovarian cancer (HR = 0.058, p = 0.018)." (PMID 38114558, 2023).
breast carcinoma (1 paper, 2024). "In addition to Rab5A, two proteins associated with cell motility, focal adhesion formation and cell-cell adhesion including ACTBL2 and CTNNA2 were also downregulated in breast cancer cells exposed to CB agonists." (PMID 39527598, 2024).
Coronary Artery Disease (1 paper, 2025). "For Coronary Artery Disease (CAD), five genes intersected between RFE and DEA analyses: CSNK1A1, AKAP5, TOPORS, ACTBL2, and FNTA." (PMID 40287491, 2025).
tumor (6 papers, 2019 to 2023). "Comprehensive analyses confirmed a statistically independent prognostic disadvantage for EOC patients with impaired overall survival upon positive ACTBL2-expression in the according tumor cells." (PMID 38114558, 2023). "After proving the successful downregulation of ACTBL2 by both qPCR and immunocytochemistry, functional assays were executed to assess its impact on tumor cell biology." (PMID 34631538, 2021). "Despite the given findings, the extent to which ACTBL2 is expressed in tumor-infiltrating leukocytes as cells with high migratory potential and activity remains to date unknown." (PMID 38114558, 2023). "Despite growing evidence on its crucial and fundamental impact on cellular motility, the extent to which ACTBL2 is expressed in tumor-infiltrating and thus migrating leukocytes (TILs) remains to date unknown." (PMID 38114558, 2023). "By examining the presence of ACTBL2-positive TILs in 156 EOC specimens via immunohistochemistry we could demonstrate that the expression of ACTBL2 in leukocytes was remarkably higher than its level in the according tumor cells." (PMID 38114558, 2023). "Apart from studies focusing on promigratory effects in biomechanically activated VSMCs, the regulatory impact of NFAT5 on ACTBL2 in tumor cells and the extent of the consequently provided alterations of cellular functions remain still unknown." (PMID 34631538, 2021). "Aiming at a particular identification of the predominant cell types and the accordingly conveyed tumor-modulating effects, additional staining analyses of the present EOC patient cohort defined the subset of ACTBL2-positive TILs as CD44-expressing cytotoxic T-cells (CD8 +) and macrophages (CD68 +)." (PMID 38114558, 2023).
cancer (3 papers, 2016 to 2025). A tumor composed of atypical neoplastic, often pleomorphic cells that invade other tissues. "In addition, Actin Beta Like 2 (ACTBL2), a novel actin isoform, was also validated because of the high Log2 Fold changes in cells across the three solid stress pressures and its reported role in cancer cell." (PMID 40371393, 2025).
ACTBL2 also shares sentences with these, for which no sentence is quoted: colorectal adenocarcinoma (1 paper); colorectal cancer (1); depression (1); leukemia (1); lymphoma (1); major depressive disorder (1); Obesity (1).